YY2 (YY2 transcription factor)
Description:
Functions as a multifunctional transcription factor that may exhibit positive and negative control on a large number of genes. May antagonize YY1 and function in development and differentiation.
Synonyms: ZNF631
Tractability: PROTAC: ubiquitination databases record sites on it.
Gene: Protein-coding gene on chromosome X (21,855,987 to 21,858,740, forward strand). Ensembl gene ENSG00000230797.
Subcellular location: Nucleus
Subcellular location (Human Protein Atlas): Nuclear bodies; Nucleoplasm
Gene Ontology:
Molecular function: cis-regulatory region sequence-specific DNA binding; DNA-binding transcription activator activity, RNA polymerase II-specific; sequence-specific DNA binding; sequence-specific double-stranded DNA binding; DNA-binding transcription factor activity, RNA polymerase II-specific; RNA polymerase II cis-regulatory region sequence-specific DNA binding
Biological process: positive regulation of transcription by RNA polymerase II; regulation of transcription by RNA polymerase II
Cellular component: nucleus; PcG protein complex; transcription regulator complex
Homologues: Orthologues: macaque YY2 (82% identical), Drosophila melanogaster phol (37% identical), Caenorhabditis elegans ztf-17 (19% identical). Paralogues in human: YY1 (60% identical), ZFP42 (36% identical).
Diseases named in the same sentence as YY2 in open-access papers:
YY2 is named in the same sentence as 25 diseases in open-access papers, as found by Europe PMC text mining. Sharing a sentence is not in itself a finding about the gene and the disease. The quoted sentences say what the papers report.
glioma (6 papers, 2020 to 2023). A benign or malignant brain and spinal cord tumor that arises from glial cells (astrocytes, oligodendrocytes, ependymal cells). "Taken together, the TAF15/LINC00665/MTF1(YY2)/GTSE1 axis has been acknowledged as an important axis in the modulation of the malignant features of glioma cells." (PMID 36429005, 2022). "The PABPC1-BDNF-AS-RAX2-DLG5 axis was shown to play the same role as the TAF15/LINC00665/MTF1(YY2)/GTSE1 axis in regulating the biological behavior of gliomas." (PMID 34178684, 2021). "For example, LINC00665 is downregulated in glioma and mediates STAU1-mediated MTF1 and YY2 stability, affecting malignant biological behavior of glioma." (PMID 32851059, 2020). "Moreover, MTF1 and YY2 transcription factor have been shown to be over-expressed in glioma cells, and their silencing has suppressed malignant behaviors of these cells." (PMID 36429005, 2022). "Finally, MTF1 or YY2 silencing has reduced expression of GTSE1 oncogene in glioma." (PMID 36429005, 2022). "Additionally, the TAF15/LINC00665/MTF1(YY2)/GTSE1 axis is crucial for regulating the malignant biological behaviors of glioma cells, which might help in the development of a novel therapeutic strategy for human glioma." (PMID 34178684, 2021). "Additionally, overexpression of TAF15 stabilizes LINC00665, leading to reduced STAU1-mediated mRNA degradation of both MTF1 and YY2, thereby restricting GTSE1 transcription and ultimately disrupting glioma’s malignant progression." (PMID 37403043, 2023). "However, another view is that LINC00665 can act as a protective factor for glioma, inhibiting the malignant development of the tumor through the TAF15|LINC00665/MTF1|YY2/GTSE1 axis." (PMID 35563845, 2022). "In glioma, the TAF15|LINC00665/MTF1|YY2/GTSE1 axis inhibits malignant tumor progression.TATA-box-binding protein-associated factor 15 (TAF15) is a member of the FET family and plays an important role in regulating mRNA transcription, RNA splicing, and trafficking." (PMID 35563845, 2022). "A recent study on glioma cell lines (U251 and U87) further demonstrated that STAU1 blocks cell migration and invasion by degrading metal regulatory transcription factor 1 (MTF1) and YY2 transcription factor (YY2) through SMD." (PMID 34633481, 2021).
breast carcinoma (3 papers, 2017 to 2022). "We observed an increase of YY1 protein expression level in MDA-MB-231 and MCF-7 cells compared with MCF-10A cells; while YY2 expression level in breast cancer cell lines was robustly decreased." (PMID 28903375, 2017). "To elucidate the role of YY2 in tumorigenesis, we first compared the expression levels of YY1 and YY2 in human clinical breast carcinoma tissues and the corresponding normal adjacent tissues." (PMID 28903375, 2017). "Our results showed that similar to that of YY2, the expression of Mbtps2 was downregulated in breast cancer cell lines." (PMID 28903375, 2017). "In contrast, aberrantly low YY2 expression at both mRNA and protein levels could be found in breast carcinoma, colon carcinoma and hepatocellular carcinoma." (PMID 32969187, 2020). "YY2 and Mbtps2 showed similar spatial expression patterns in the brain, ovary and testis, as well as in breast cancer cell lines, indicating that these two genes might be subjected to similar transcriptional control." (PMID 32969187, 2020). "To elucidate the role of YY2 in tumorigenesis, we first constructed a YY2 overexpression vector, and confirmed its expression in HCT116 colorectal cancer cells, MHCC‐97H hepatocarcinoma cells and MCF‐7 breast cancer cells." (PMID 35246964, 2022). "Next, to further confirm the different expression profiles of YY1 and YY2 in normal and tumor cells, we compared the expression levels of YY1 and YY2 in normal mammary epithelial cell line (MCF-10A) and breast cancer cell lines (MCF-7 and MDA-MB-231)." (PMID 28903375, 2017).
colorectal cancer (3 papers, 2022 to 2025). A primary or metastatic malignant neoplasm that affects the colon or rectum. "Our results showed that YY2/BUB3 axis positively modulates SAC activity, prolongs mitotic time, and suppresses colorectal cancer (CRC) cells survival." (PMID 38682484, 2024). "Based on RNA‐Seq results, we further examined whether YY2 affected cell death and lipid peroxidation, an initial step in ferroptosis, using HCT116, LoVo, and HT29 colorectal cancer cells." (PMID 35246964, 2022). "Next, we analyzed the link between YY2 and SLC7A11 in clinical colorectal cancer tissues." (PMID 35246964, 2022). "Moreover, its expression was conspicuously lower in colorectal cancer lesions compared to adjacent tissue, suggesting a negative correlation between YY2 and tumor progression." (PMID 35246964, 2022).
liver cancer (2 papers, 2023 to 2024). An epithelial or non-epithelial malignant neoplasm that arises from the liver. "It is shown that YY2 is downregulated in stem‐like tumor spheres formed by hepatocarcinoma cells and in liver cancer, in which its expression is negatively correlated with disease progression and poor prognosis." (PMID 37300334, 2023). "Finally, our study points to YY2 as a novel therapeutic target for liver cancer." (PMID 37300334, 2023).
Obesity (2 papers, 2023 to 2026). Accumulation of substantial excess body fat. "Thus, a novel obesity‐associated TRIM15/YY2/FOXRED1 axis is identified that contributes to the proliferation of EAC." (PMID 41237333, 2026).
bile duct cancer (1 paper, 2025). "The TIMER analysis demonstrated a significant upregulation of YY2 expression in various tumor types, including ESCA, bile duct cancer, and rectal cancer, compared to normal tissues." (PMID 41235100, 2025).
breast invasive carcinoma (1 paper, 2020). "Similarly, the motifs CGR (breast invasive carcinoma), CACAAR (glioblastoma multiforme), ATGWTG (lung squamous cell carcinoma), CGWCCGAA (prostate adenocarcinoma) show exclusive affinity for YY2, RUNX1, ATF4 and ZBTB7B, respectively." (PMID 32015379, 2020).
cardiac hypertrophy (1 paper, 2020). "However, conditional expression of YY2 did not induce discernible cardiac hypertrophy in dTg mice." (PMID 32195266, 2020).
heart failure (1 paper, 2020). Inability of the heart to pump blood at an adequate rate to meet tissue metabolic requirements. "Our findings show that the conditional cardiac expression of YY2 induces partial embryonic lethality and results in cardiomyopathy and heart failure that occurs with aging." (PMID 32195266, 2020). "Our findings indicate that YY2 is involved in promoting the pathogenesis of cardiomyopathy and suggest that YY2 may be a therapeutic target for the treatment of heart failure." (PMID 32195266, 2020). "Because autophagy and JNK activity are important for maintaining cardiac homeostasis, the dysregulation of these signaling pathways may contribute to YY2-induced cardiomyopathy and heart failure in vivo." (PMID 32195266, 2020).
status epilepticus (1 paper, 2015). Status epilepticus is defined as a continuous seizure lasting more than 30 min, or two or more seizures without full recovery of consciousness between any of them. "Here, we explored the transcriptional response of genes associated with polycomb repressive complex (PRC) 1 (Ring1A, Ring1B, and Bmi1) and PRC2 (Ezh1, Ezh2, and Suz12), as well as additional transcriptional regulators Sirt1, Yy1, and Yy2, in a mouse model of status epilepticus (SE)." (PMID 25806020, 2015).
tumor (16 papers, 2017 to 2026). "The transcription factor YY2 plays a pivotal role in various tumor-associated biological processes, including cellular proliferation, metastasis, metabolic reprogramming, immune regulation, and immune surveillance." (PMID 41235100, 2025). "YY2 downregulation has been found in various cancers and is correlated with poor prognosis, thus, our findings demonstrate novel mechanism underlying its tumor suppressive effect." (PMID 39903759, 2025). "Meanwhile, YY2 knock‐out in stem‐like tumor spheres caused enrichment in mitochondrial functions." (PMID 37300334, 2023). "Furthermore, mutations in YY2 zinc‐finger domains, which potentially could be found in clinical tumor patients, abrogated the YY2/SLC7A11 axis, leading to a decline of ferroptosis." (PMID 35246964, 2022). "Thus, while further investigations are needed, these mutations might contribute to YY2 downregulation and loss‐of‐function in human tumor tissues, and subsequently, to clinical tumor development." (PMID 35246964, 2022). "Further studies revealed that TRIM15 promotes tumor progression by mediating the ubiquitination and subsequent degradation of YY2, disrupting lipid and energy metabolism regulation in EAC cells by inhibiting FOXRED1 transcription." (PMID 41237333, 2026). "Given that YY2 co-expressed genes are associated with glycometabolism and glycolysis, a critical metabolic pathway for tumor cell growth and survival, a regulatory network involving YY2 in the glycolysis pathway was constructed." (PMID 41235100, 2025). "Although certain studies have highlighted its oncogenic potential, YY2 has primarily been characterized as a tumor suppressor gene in the majority of studies." (PMID 41235100, 2025). "Meanwhile, combination of anti‐PD‐L1 antibody with YY2 overexpression significantly reduced the tumor volume." (PMID 39903759, 2025). "Our results confirm for the first time that YY2 functions as a tumor promoter in ESCA through knockdown experiments in ESCA cell lines." (PMID 41235100, 2025). "Our results show that YY2 is a mitotic checkpoint regulator and, therefore, adjusting chromosome missegregation by controlling YY2 expression is a potential anti‐tumor strategy." (PMID 39903759, 2025). "Increased infiltration of immune cells was confirmed by numerous CD45+ cells in the tumor lesions formed by YY2‐overexpressing cells." (PMID 39903759, 2025). "LMNB2 overexpression attenuated the YY2 tumor suppressive effect, while blocking caspase‐1/GSDMD activation, IL‐1β levels, and cell death rate." (PMID 39903759, 2025). "Subsequently, we examined the effect of LMNB2 overexpression on the YY2 tumor suppressive potential in vivo." (PMID 39903759, 2025). "This methylation regulates the DNA-binding capacity of YY2 and chromosomal interactions, influencing gene transcription, cellular proliferation, and tumor growth." (PMID 41235100, 2025). "We then assessed the possibility of combining excessive CIN induced by YY2 overexpression with oxaliplatin for anti‐tumor therapeutic strategy in vivo." (PMID 38682484, 2024). "Together, our results demonstrated that YY2/SAC hyperactivation induces CIN in tumor cells, leading to the mortality of cells with excessive CIN." (PMID 38682484, 2024). "The suppressive effect was further enhanced by combining YY2 overexpression and oxaliplatin treatment, which suppressed the increase in tumor volume to only two‐fold." (PMID 38682484, 2024). "In contrast, the induction of excessive CIN in those cells by YY2 overexpression sensitizes them to DNA damage‐inducing agents, suggesting a novel anti‐tumor therapeutic approach by combining SAC activator and DNA damage‐inducing agents." (PMID 38682484, 2024). "Our findings showed that residual tumor cells that survived DNA damage‐inducing agents as well as YY2‐induced SAC hyperactivation, possess moderate CIN and are more resistant." (PMID 38682484, 2024).
tumor (continued). "Instead, treatment with mDivi‐1 inhibited the increase in stem‐like tumor spheres seen in YY2 knock‐out HCC‐LM3 cells, and similarly, in YY2 knock‐out MHCC‐97H cells." (PMID 37300334, 2023). "Staining with MitoTracker Red, a ΔΨm‐dependent mitochondria marker, and MitoTracker Green, a ΔΨm‐independent mitochondria marker, revealed that YY2 overexpression clearly reduced ΔΨm in stem‐like tumor spheres formed by HCC‐LM3 and MHCC‐97H cells." (PMID 37300334, 2023). "Compared to wild‐type stem‐like tumor spheres, 1465 genes were differentially expressed in YY2 knock‐out tumor spheres: 528 of them were upregulated and 937 were downregulated." (PMID 37300334, 2023). "KEGG analysis showed that “oxidative phosphorylation” and “citrate cycle (TCA cycle)” were enriched in YY2 knock‐out stem‐like tumor spheres, hinting at a possible regulatory role of YY2 in mitochondrial function." (PMID 37300334, 2023). "Downregulation of YY2 mRNA and protein levels in stem‐like tumor spheres compared to adherent cells was further validated in HCC cell lines." (PMID 37300334, 2023). "Together, these results indicate that YY2 negatively regulates tumor stemness by suppressing mitochondrial fission." (PMID 37300334, 2023). "YY2 overexpression clearly decreased the number of tumor spheres formed by HCC‐LM3 and MHCC‐97H and cells, as well as the frequency of liver CSCs in the spheres from 1:4 to 1:13 and 1:11, respectively." (PMID 37300334, 2023). "The negative regulation of DRP1 by YY2 in stem‐like tumor spheres was confirmed by DRP1 protein expression." (PMID 37300334, 2023). "We report that YY2 impairs asymmetric stem cell division and promotes the generation of more differentiated progeny from liver CSCs, thereby suppressing the tumor‐initiating capacity and tumorigenesis of CSCs." (PMID 37300334, 2023). "DRP1 overexpression restored the levels of CSC markers, as well as the number of tumor spheres suppressed by YY2 overexpression." (PMID 37300334, 2023). "In contrast, knocking out YY2 robustly increased the number of tumor spheres formed by HCC‐LM3 and MHCC‐97H cells, as well as the frequency of liver CSCs from 1:4 to 1:1." (PMID 37300334, 2023). "Compared to the corresponding adjacent tissue, YY2 was downregulated in tumor lesions; whereas DRP1 expression was significantly increased." (PMID 37300334, 2023). "YY2 overexpression increased the proportion of HCC‐LM3 and MHCC‐97H stem‐like tumor spheres containing elevated green fluorescence or cells with dysfunctional mitochondria; whereas YY2 knock‐out decreased them." (PMID 37300334, 2023). "We next validated the expression levels of these two factors, and the results showed a higher fold‐change of YY2 expression in adherent and stem‐like tumor spheres compared to GTF2H4." (PMID 37300334, 2023). "DRP1 colocalization with Tom20 was low in YY2‐overexpressed HCC‐LM3 cells and high in YY2 knock‐out cells obtained from stem‐like tumor spheres, indicating that YY2 suppressed DRP1 distribution in the mitochondrial network of liver CSCs." (PMID 37300334, 2023). "Overall, these results indicate that mutations in the YY2 zinc‐finger domains as found in clinical tumor patients abrogated the YY2/SLC7A11 axis, and consequently, abrogated the effect of YY2 on tumor cell ferroptosis." (PMID 35246964, 2022). "Our findings highlight an unprecedented relationship between YY2, amino acid metabolism, and ferroptosis, and show the critical role of YY2‐mediated regulation of ferroptosis on the tumor suppressive effect of YY2." (PMID 35246964, 2022). "To elucidate the molecular mechanism underlying the tumor suppressive effect of YY2, we performed RNA sequencing (RNA‐Seq: GSE184138) to identify the genes differentially regulated by YY2." (PMID 35246964, 2022).